FGF21 (fibroblast growth factor 21)
Diseases named in the same sentence as FGF21 in open-access papers (continued):
Sharing a sentence is not in itself a finding about the gene and the disease.
Obesity (continued). "Given that our novel observations demonstrate the direct effect of FGF21 in the heart and differences in obesity, a detailed analysis of the FGFR1-FGF21-βKlotho signalling pathway is crucial." (PMID 24498293, 2014). "In light of the potential clinical significance of FGF21 and irisin/FNDC5 for the treatment of obesity, an understanding of their regulation is of obvious importance." (PMID 24603718, 2014). "Hormone resistance to the effects of insulin, leptin, and fibroblast growth factor 21 (FGF21) has been reported in diabetes and obesity." (PMID 23409033, 2013). "FGF21 and FGF19 are potent regulators of glucose, lipid and energy metabolic homeostasis and suppress obesity and diabetes through targeting adipose tissue and liver." (PMID 24279986, 2013). "Fibroblast growth factor 21 (FGF21) is a novel class of drug candidates for the treatment of metabolic disorders, including type 2 diabetes and obesity." (PMID 23209571, 2012). "Recent studies suggest that betaKlotho (KLB) and endocrine FGF19 and FGF21 redirect FGFR signaling to regulation of metabolic homeostasis and suppression of obesity and diabetes." (PMID 22442730, 2012). "In an effort to compare efficacy of the factors in another model of obesity we examined the effects of chronic FGF19 and FGF21 infusion in ob/ob mice." (PMID 22675463, 2012). "The physiologic importance of FGF21 is evident from studies showing that systemic administration of FGF21 reduces serum and liver triacylglycerol (TAG) concentrations, body weight and obesity in obese mice." (PMID 22394566, 2012). "For example, administration of both, PPARα agonists such as fibrates and FGF21 lowered LDL-cholesterol, raised HDL-cholesterol, improved insulin sensitivity and prevented diet-induced obesity in rhesus monkeys and rodents." (PMID 22394566, 2012). "Because the FGF-21 molecule has a circadian rhythm disrupted by a high-fat diet, intermittent fasting has been claimed to have the benefit of rebalancing FGF-21 release and, thus, potentially preventing obesity." (PMID 40430125, 2025). "Additionally, it would be of interest to explore in future studies variations in the levels of FGF21 and GDF15, considering obesity and severe obesity as separate disease entities, as it has been shown that their pathophysiology can differ significantly." (PMID 40377893, 2025). "In addition to their independent effects regulating metabolism, in the present study, we uncovered that FGF21 and GDF15 act synergistically to improve glucose homeostasis and promote resistance to diet‐induced obesity." (PMID 40897647, 2025). "FGF21, a recently recognized metabolic regulator of glucose and lipid metabolism as well as energy homeostasis, has gained significant attention as a promising therapeutic agent for metabolic disorders, including NASH, T2DM, and obesity." (PMID 40756666, 2025). "Another study showed that diet induced obesity in FGF21 liver‐specific but not FGF21 adipocyte‐specific KOs led to an increased insulin resistance but decreased brown adipose tissue‐mediated glucose metabolism." (PMID 39962359, 2025). "Additionally, administration of MB109, a recombinant derivative of human BMP9, in obese mice enhances FGF21 expression, alleviates HFD-induced obesity, and reduces liver lipid droplets." (PMID 40243151, 2025). "Our current results also showed that Fgf21 was significantly upregulated in the DIO + DHA group, suggesting that the beneficial effects of this n-3 PUFA on age and obesity-related MASLD could be mediated, at least in part, by Fgf21 upregulation." (PMID 41373837, 2025). "Accordingly, men with obesity had lower serum cortisol and higher plasma FGF21 levels than lean controls did, independent of their HH status." (PMID 39885510, 2025). "The authors of this study also supported that FGF-21 resistance may inhibit any counterbalancing effects of FGF-21 changes not only in NAFLD, but also in obesity and T2DM, which is in accordance with our speculation above." (PMID 40465044, 2025).
Obesity (continued). "In combination with PPARα activation, better improvement was achieved for obesity, insulin resistance, and hepatic steatosis, independent of FGF21 induction." (PMID 40815899, 2025). "This functionality is the basis for developing FGF21-based therapeutics and dual agonists, such as those combining FGF21 with glucagon-like peptide-1 (GLP-1), which are being explored for their efficacy in treating obesity and related metabolic disorders." (PMID 39194718, 2024). "However, it’s noteworthy that heightened endogenous FGF21 levels have been documented in people with obesity, NAFLD, and diabetes, indicative of a state of FGF21 resistance." (PMID 38609395, 2024). "Several studies have indicated that, while circulating FGF21 levels are elevated, its signal transduction and actions are impaired in the skeletal muscles of patients with T2DM and insulin-resistant human skeletal muscle myotubes with diet-induced obesity." (PMID 39640300, 2024). "Reviewing literature, no studies were found to assess the relation between FGF-21 and Visfatin as potential markers for obesity and its metabolic disorders in both children and adolescents." (PMID 38216702, 2024). "Thus, the induction of FGF21 can be a possible therapeutic strategy for treating IR and obesity, while inhibiting HDAC is one way to increase the expression of FGF21." (PMID 38534427, 2024). "According to a study in mice, semaglutide treatment may stimulate FGF21 in mouse liver and improve FGF21 sensitivity, suggesting an important role of the GLP-1/FGF21 axis in mediating beneficial effects in obesity." (PMID 39728000, 2024). "It has been shown that in transgenic mice with an overexpression of the fgf21 gene, a high-fat diet does not lead to the development of obesity." (PMID 39064306, 2024). "In our study, although FGF21 levels were higher in individuals with metabolically healthy obesity, no statistical difference was found between FGF21 levels of participants with metabolically healthy and unhealthy obesity." (PMID 39008201, 2024). "Additionally, SIRT1 activation can prevent liver steatosis by inducing the expression of fibroblast growth factor 21 (FGF21), a hormone produced by hepatocytes that restores glucose and lipid homeostasis in obesity-induced diabetes." (PMID 38247843, 2024). "Collectively, these findings demonstrate that the defense against overfeeding-induced weight gain remains intact in obesity and involves mechanisms independent of both FGF21 and MC4R." (PMID 38331907, 2024). "In our research, aside from BW, we did not assess various blood-based parameters to confirm obesity in all aspects or serum FGF21 levels." (PMID 38673797, 2024). "In studies comparing individuals with and without obesity, FGF21 levels were correlated within BMI and fat mass." (PMID 39008201, 2024). "The expected beneficial effects of endogenous FGF21 are not present in obesity, which is a great challenge for clinical drug development based on FGF21." (PMID 37424900, 2023). "We examined 11 target cytokines (IL‐1b, TNF‐a, CRP, secreted protein acidic rich in cysteine [SPARC], fibroblast growth factor 21 [FGF21], IL‐6, IL‐8, IL‐10, IL‐13, IL‐15, and IL‐18) known to be altered in the presence of obesity and/or T2D, and to be regulated by acute and/or chronic exercise." (PMID 36905198, 2023). "SFD consumption and obesity development were accompanied by increases in the plasma concentrations of glucose, insulin, and FGF21 in mice of both sexes, regardless of maternal obesity." (PMID 36982684, 2023). "FGF21-based drugs as well as FGF21 and GLP1 dual agonists, have been developed to treat obesity." (PMID 36594101, 2023). "We cannot conclude on the events of the immediate post-operative period; however, after > 1 year, decreased FGF-21 levels were observed in patients without obesity compared with those with obesity, which is consistent with previous studies." (PMID 36462120, 2023).
Obesity (continued). "Hale C., Chen M.M., Stanislaus S., Chinookoswong N., Hager T.,Wang M., Véniant M.M., Xu J. Lack of overt FGF21 resistance intwo mouse models of obesity and insulin resistance." (PMID 37469453, 2023). "Furthermore, key risk factors for NAFLD, including insulin insensitivity, obesity, and dyslipidemia, are alleviated by FGF-21, and FGF-21 has been reported to reverse liver steatosis while counteracting obesity and enhancing insulin sensitivity." (PMID 38222178, 2023). "Plasma FGF21 levels of the CORT-treated group, however, were comparable between GRfl/fl and GR-mKO mice in both the fed and fasted states, indicating that other axes rather than hepatic FGF21 production are probably dominant regulators in this obesity model." (PMID 36917179, 2023). "Additionally, fibroblast growth factor 21 (FGF21), a key mediator of fatty acid oxidation and lipid metabolism, which has been demonstrated to enhance WAT browning, is reduced in obesity." (PMID 37076885, 2023). "In our study, elevated CK-18 plasma levels were accompanied by elevated FGF-21 levels in obesity, whereas FGF-19 was not related." (PMID 37189422, 2023). "Unexpectedly, FGF21 LKO completely abrogated OVX-induced central obesity but not these obesity-related metabolic disorders." (PMID 37834368, 2023). "Interestingly, miRNA-34a suppresses the thermogenesis in obesity through partially regulating SIRT1 and fibroblast growth factor 21 (FGF21), another muscle factor recently discovered in browning of sWAT." (PMID 37138165, 2023). "Long-term induction of GDF15 in this model was required to attenuate the progression of obesity by increasing energy expenditure, while FGF21 did not affect energy expenditure, but remarkably ameliorated DIO and insulin resistance." (PMID 37818094, 2023). "Brain-derived neurotrophic factor (BDNF), secreted protein acidic and rich in cysteine (SPARC), fibroblast growth factor 21 (FGF-21), growth differentiation factor 15 (GDF-15) are examples of such cytokines which have therapeutic potential in obesity and metabolic diseases." (PMID 37436597, 2023). "Moreover, FGF21 stimulates the browning of white AT by increasing PGC1α-dependent UCP-1 expression, which potentially contributes to its metabolic benefits in obesity and diabetes." (PMID 35909571, 2022). "In the mice lacking β-KL, FGF21 was defective in regulating lipid and glucose metabolism at the whole organism level in diet-induced obesity." (PMID 35983184, 2022). "The endocrine subfamily of FGFs, consisting of FGF19, FGF21, and FGF23, might have beneficial effects in the treatment of diabetes mellitus (DM) and/or obesity." (PMID 36699319, 2022). "Furthermore, FGF21 has been found to promote the metabolic events leading to type 2 diabetes mellitus, NAFLD, and obesity." (PMID 36140410, 2022). "Fibroblast growth factor 21 (FGF21) is widely expressed in various organs, including the liver, pancreas, skeletal muscle, and adipose tissues, but circulating FGF21 in diet-induced obesity and type 2 diabetes is liver-derived." (PMID 35163521, 2022). "The phenomenon of increased FGF21 levels and resistance to diet induced obesity in UCP1 KO mice is only seen at mild cold, not thermoneutral conditions." (PMID 36034414, 2022). "Thus, the increase FGF21 in plasma and tissues following melatonin contribute to fat utilization and BAT activity in obesity." (PMID 36207302, 2022). "Therefore, the purpose of this study was to investigate to which extent obesity-associated NAFLD and accompanying inflammatory processes are reversible by treadmill training, dietary change, and/or time-restricted feeding, and whether this is associated with enhanced hepatic FGF21 sensitivity." (PMID 36034917, 2022). "In murine models of T2DM and obesity, GLP-1-Fc-FGF21 D1 improved liver function, serum and hepatic lipid profiles, and reduced body weight and NAS scores with an efficacy superior to either FGF21 or GLP1R agonists alone." (PMID 35203484, 2022).
Obesity (continued). "It has been shown that TNF-α acts through the TNF-α-JNK1 axis to inhibit the effects of FGF21 in AT, suggesting that a combination of FGF21 and JNK1 inhibitors could be a potential therapeutic strategy in obesity." (PMID 35909571, 2022). "In participants who mostly remained with obesity despite conventional (non-surgical) anti-obesity measures, C1QTNF1, FGF-21 and CST3 were associated with a significantly higher risk of HF compared with those who lost weight through surgical intervention." (PMID 35945262, 2022). "For this purpose we determined serum FGF-19 and FGF-21 concentrations in obese rats, whose role in the pathogenesis of obesity is not yet established." (PMID 36362225, 2022). "Grade II obesity patients had the highest circulating concentrations of FGF21 (729.6 ± 200.9 pg/mL) and RBM3 (408.8 ± 133.9 pg/mL), while patients with a BMI of <25 presented with the lowest values (FGF21 = 311.7 ± 192.9 pg/mL; RBM3 = 285.5 ± 122.2 pg/mL)." (PMID 35207221, 2022). "Similarly, among the 15 anti-inflammatory organokines, 7 (adiponectin, Omentin-1, ZAG, SFRP5, CTRP3, IL-10, and DEL-1) showed reduced levels and 8 (LCN2, VASPIN, IL-1RA, FGF21, GDF15, MANF, Irisin, and IL-6) showed elevated levels in patients with obesity." (PMID 35909571, 2022). "Plasma 5-HT and FGF21 levels are increased in rodents and humans with obesity, type 2 diabetes, and non-alcohol fatty liver diseases (NAFLD)." (PMID 35163521, 2022). "In humans with obesity or cardiometabolic disease FGF21 is elevated, indicating potential FGF21 resistance, with no increase with ketogenesis." (PMID 36145067, 2022). "Infemale C57Bl mice with obesity induced by the consumptionof high sweet-fat diet, FGF21 reduced body weight, but, unlikemales, did not affect glucose tolerance or the expressionof metabolic genes in the liver or in brown adipose tissue." (PMID 35434487, 2022). "Finally, we propose that silencing Mat1a in obesity activates NRF2 in hepatocytes and induces the secretion of FGF21 to the general circulation, which increases WAT lipolysis and BAT thermogenesis, decreasing de novo lipogenesis in the liver." (PMID 35232994, 2022). "Additionally, the liver-specific deletion of the mitochondrial fission regulator Drp1 induces the expression of FGF21, a hormone that is secreted by the liver, which in turn increases energy expenditure and protects animals against HFD-induced obesity." (PMID 39871928, 2022). "Nevertheless, increased levels of serum FGF21 are reported in individuals with obesity and/or T2DM,211, 212 suggesting FGF21 resistance may have developed over time." (PMID 35856338, 2022). "According to our data, there were not significant changes in bile acid total pool with only changes in two individual species, yet FGF-21 levels were consistently elevated among PCOS patients independent of obesity in coordination with TCA levels." (PMID 36204478, 2022). "Notably, FGF21 and the FGF21 receptor complex (FGFR1c and KLB) knockout mouse models indicate that glucagon requires the FGF21 pathway to protect from obesity." (PMID 35547006, 2022). "A study with 70 children with obesity and 45 without obesity showed that FGF-21 levels were significantly correlated with HOMA-IR after adjusting for BMI, TG, HDL, and adiponectin levels." (PMID 34946319, 2021). "As AAV‐FGF21 gene therapy have resulted in marked reductions in bodyweight and insulin resistance in HFD feeding and ob/ob mice, FGF21 can be a potential target to treat obesity and insulin resistance." (PMID 34227742, 2021). "In Ay mice with genetically induced obesity, females, unlike males, were resistant to the catabolic effects of FGF21." (PMID 34638898, 2021). "Replenishing FGF21 KO mice with obesity-mimicking levels of recombinant FGF21 for 4 weeks did not alter body weight, but restored subcutaneous fat mass after 8 weeks of HFD, suggesting that FGF21 is important for subcutaneous fat expansion in obesity." (PMID 35046901, 2021).
Obesity (continued). "Despite the fact that females differed from males in degree of obesity and consumption of a high-fat diet, sex did not influence the pharmacological action of FGF21." (PMID 34638898, 2021). "Our study identifies a potentially novel miR-182-5p/FGF21/acetylcholine/PKA signaling circuit that mediates the crosstalk between adipocytes and adipose tissue–resident macrophages to promote beige fat development and counteract overnutrition-induced obesity." (PMID 34264867, 2021). "Indeed, we show that feeding mice a diet supplemented with sodium selenite results in an MR-like phenotype, marked by protection against diet-induced obesity, as well as altered plasma levels of IGF-1, FGF-21, adiponectin, and leptin." (PMID 33783357, 2021). "Third, mice with transgenic KLB overexpression are not protected from diet-induced obesity, despite the prediction that they would be more FGF21-sensitive." (PMID 35046901, 2021). "This preclinical study is the first to show that sex-specific metabolic features in mice with diet-induced obesity do not significantly affect the pharmacological effects of FGF21." (PMID 34638898, 2021). "Further, it is still not clear why FGF21 administration tends to improve metabolic endpoints, yet FGF21 levels are paradoxically increased with metabolic conditions such as obesity, type 2 diabetes, and cardiovascular disease." (PMID 35046901, 2021). "Individuals with obesity, in whom protective effects are not shown with increased serum levels of FGF21, are considered FGF21-resistant." (PMID 34799626, 2021). "Together, these data demonstrate that our method of nonviral in vivo FGF21 gene therapy protects against the effects of diet-induced obesity." (PMID 34074713, 2021). "Thus, our results indicate that a decreased FGF-21 level cannot suppress SREBP1 expression or hepatic and serum triglyceride levels, consequently engendering obesity and fatty liver disease." (PMID 34206460, 2021). "In children with obesity, FGF-21 decreases after the implementation of an intervention program of weight loss, while in adolescents with diabetes mellitus type 2 (DM2), FGF-21 concentrations are higher than in those without DM2." (PMID 33924457, 2021). "We also demonstrate that nonviral FGF21 gene delivery protected against diet-induced obesity in mice." (PMID 34074713, 2021). "Brown adipose tissue (BAT)-derived fibroblast growth factor 21 (FGF21) does not mediate resistance to diet-induced obesity in optic atrophy 1 (OPA1) BAT knockout (KO) mice." (PMID 33944779, 2021). "As a peripheral hormone, FGF21, another mediator of the ISR, has anti-obesity effects." (PMID 34877504, 2021). "In this review, we will focus on the interplay of obesity (e.g., adipose tissue dysfunction and meta-inflammation), oncogenic KRAS, and metabolic and inflammatory regulators, in particular FGF21, a novel anti-obesity and anti-inflammation factor, in the development of PDAC." (PMID 33668583, 2021). "Nevertheless, a clear consensus regarding the physiological role (if any) played by the increased FGF21 observed in obesity and/or NASH is still lacking." (PMID 35046901, 2021). "Additionally, a recombinant human FGF21, PEGylated rhFGF21 (PEG-rhFGF21), has been developed for the treatment effect on diabetic nephropathy in diet induced obesity animal model." (PMID 34675822, 2021). "Thus, this discovery opens new opportunities for structurally-based therapeutic agents of FGF21 for selective metabolic disorders such as T2DM and obesity." (PMID 34572066, 2021). "FGF21, GDF15, as well as VEGF and IL6, have been associated individually with a range of non-mitochondrial diseases, encompassing cancer, obesity, renal disease, diabetes, and liver disease, although many of them are characterized by an OXPHOS dysfunction." (PMID 32397676, 2020).